SCN8A (sodium voltage-gated channel alpha subunit 8)
Diseases named in the same sentence as SCN8A in open-access papers (continued):
Sharing a sentence is not in itself a finding about the gene and the disease.
epilepsy (continued). "Variants in SCN8A are associated with a spectrum of epilepsies and neurodevelopmental disorders." (PMID 38251463, 2023). "While the neurodevelopmental and epilepsy phenotype of SCN8A is well established, the spectrum of SCN8A-associated movement disorders is less well understood and SCN8A variants may represent an underdiagnosed aetiology of hereditary ataxia." (PMID 38251463, 2023). "For example, KCNQ2, KCNQ3, SCN1A, SCN2A, and SCN8A are associated with phenotypes ranging from self-limited epilepsies with normal developmental outcome to intermediate severity conditions to drug-resistant epilepsies with profound developmental impairment." (PMID 37596007, 2023). "A comprehensive single-center dataset for SCN8A epilepsy that includes clinical, genetic, electrophysiologic, and pharmacologic data confirm a spectrum of severity and a variety of biophysical defects of Nav1.6 variants consistent with gain of channel function." (PMID 37880579, 2023). "Functional studies using whole-cell voltage clamp electrophysiology revealed that R639C displayed gain-of-function effects, consistent with the hypothesis that a majority of epilepsy-associated SCN8A mutations primarily result in enhanced channel function." (PMID 35805192, 2022). "•This is the first epilepsy surgery report in patient with SCN8A mutation." (PMID 35492509, 2022). "Gain-of-function mutations in the SCN8A gene encoding Nav1.6 are linked to epilepsy development; however, the molecular mechanisms mediating these changes are remarkably heterogeneous and may involve post-translational regulation of Nav1.6." (PMID 35805192, 2022). "Pathogenic variants in SCN8A have been associated with a wide spectrum of epilepsy phenotypes." (PMID 35492509, 2022). "Moreover, the molecular mechanisms and phenotypic outcomes associated with SCN8A epilepsies are remarkably heterogeneous, suggesting additional underlying molecular mechanisms beyond mutation." (PMID 35805192, 2022). "At present, voltage-gated sodium channel genes such as SCN1A, SCN2A, SCN3A, and SCN8A were reported to be causative genes of epilepsy, among them SCN2A has been reported to be the second most common, next only to SCN1A, the first reported causative gene for epilepsy." (PMID 35431799, 2022). "We describe a patient with epilepsy related to SCN8A mutation which was reported as a variant of uncertain significance at time of his pre-surgical evaluation and reclassified as likely pathogenic about 3 years after resective epilepsy surgery." (PMID 35492509, 2022). "We also showed that diverse Nav1.6 mutants displayed distinct responses to CaMKII modulation and revealed that CaMKII inhibition may attenuate gain-of-function effects commonly observed in epilepsy-associated SCN8A mutations." (PMID 35805192, 2022). "Bradycardia during and after fatal seizures has also been observed in animal models of epilepsy, including in anesthetized cats, and a number of mouse models of epilepsy, including mice with Scn8a mutations used in the present study." (PMID 35126041, 2021). "Mutations in SCN8A gene is the major underlying factor responsible for pathogenesis of SCN8A encephalopathies; a seizure disorder marked with early onset paroxysmal manifestations characterized by hypersynchronous electrical discharges originating in the brain." (PMID 33841294, 2021). "Regions of SCN8A with Functionally validated epilepsy variants with references." (PMID 33841294, 2021). "The first human SCN8A epilepsy-associated mutation (c.5302A > G, p.N1768D) was identified in a proband who presented with spontaneous seizures, behavioral deficits, and sudden unexpected death in epilepsy (SUDEP)." (PMID 34867351, 2021). "This further establish that either gain or loss-of-function mutations in SCN8A cause epilepsy." (PMID 33841294, 2021). "The first case of SCN8A pathogenic variant associated with epilepsy was reported eight years ago." (PMID 33013363, 2020).
epilepsy (continued). "Finally, SCN1A and SCN8A mutations have been associated with sudden unexpected death in epilepsy (SUDEP)." (PMID 31185666, 2019). "Six de novo mutations of SCN8A were detected in 6 sporadic patients with epilepsy." (PMID 28923014, 2017). "SCN8A mutations have recently been associated with epilepsy and neurodevelopmental disorders." (PMID 28923014, 2017). "Sodium channel blockers may be the rational candidate drugs for the treatment of epilepsy caused by SCN8A mutations, including OXC,CBZ, LTG, Phenobarbital (PB), TPM and PHT, etc.." (PMID 28923014, 2017). "With the use of whole-exome sequencing, a de novo missense mutation in SCN8A was identified in a 4-yr-old female who initially exhibited symptoms of epilepsy at the age of 5 mo that progressed to a severe condition with very little movement, including being unable to sit or walk on her own." (PMID 27900360, 2016). "Mutations in SCN8A are associated with epilepsy and intellectual disability." (PMID 26252990, 2016). "Given that SCN8A mutations are often gain-of-function and result in increased sodium currents, it was speculated that these drugs might be efficacious in SCN8A-derived epilepsy." (PMID 38895634, 2024). "Indeed, individuals with a LOF SNV in SCN8A/SCN2A, the genes encoding NaV1.6/NaV1.2, also exhibit epilepsy, and the concept that impaired inhibitory neuronal excitability results in epilepsy has been considered in the related disorder of FGF13, a member of the FGF homologous factor family." (PMID 37286232, 2023). "However, it is unknown whether acute CaMKII inhibition may attenuate gain-of-function effects and associated hyperexcitability caused by SCN8A epilepsy mutations, or if CaMKII can differentially modulate channel activity between diverse SCN8A polymorphisms." (PMID 35805192, 2022). "The role of genetic testing in predicting the prognosis for surgical outcomes in epilepsy is still evolving, and further studies on a larger patient cohort are needed to identify the role of epilepsy surgery in patients with drug-resistant epilepsy related to SCN8A mutation." (PMID 35492509, 2022). "Mutations in four evolutionary and functionally similar α subunit genes, SCN1A, SCN2A, SCN3A, and SCN8A, lead to neurological diseases, including various types of epilepsy." (PMID 41007641, 2025). "Soon thereafter the SCN8A gene was included on commercial epilepsy gene panels and an online patient registry (the International SCN8A Registry) was established." (PMID 40830973, 2025). "Contrary to earlier assumptions, structural MRI abnormalities are common in SCN-related epilepsies, particularly in SCN2A-and SCN8A-related epilepsies." (PMID 41573391, 2025). "Extensive review of the SCN8A literature (more than 460 publications since 2012) and requests for proposals from epilepsy funding agencies were performed (e.g., CURE, Epilepsy Foundation, NINDS)." (PMID 40830973, 2025). "In SCN8A-related epilepsies, common findings included atrophy (28.6%), hippocampal abnormalities (14.3%), and white matter signal abnormalities (14.3%)." (PMID 41573391, 2025). "In this single-center cohort of 139 pediatric patients with genetically confirmed SCN1A-, SCN2A-, SCN3A-, and SCN8A-related epilepsies, structural brain MRI abnormalities were identified in 37.4% of the patients." (PMID 41573391, 2025). "Abnormal MRI findings have also been reported in SCN2A, SCN3A, and SCN8A-related epilepsies, although most studies to date have been limited to case reports or small series, and imaging patterns remain poorly defined across genotypes." (PMID 41573391, 2025). "Significance: In both the epilepsy panel and WES groups, variants in sodium channel proteins, specifically in the SCN1A, SCN8A, and SCN9A genes, were found to have a high frequency." (PMID 40565516, 2025). "To address this gap, we analyzed structural brain MRI findings in a large single-center pediatric cohort with genetically confirmed SCN1A-, SCN2A-, SCN3A-, and SCN8A-related epilepsy." (PMID 41573391, 2025).
epilepsy (continued). "NBI-921352 is under development for both SCN8A-DEE epilepsy and adult focal seizures for oral administration." (PMID 41515912, 2025). "Of these, 114, 17, 1, and 7 patients had SCN1A-, SCN2A-, SCN3A-, and SCN8A-related epilepsy, respectively." (PMID 41573391, 2025). "This study is one of the largest single-center comparative neuroimaging analyses of SCN1A-, SCN2A-, SCN3A-, and SCN8A-related epilepsies." (PMID 41573391, 2025). "We selected the RL/+ mutants for this in vivo drug screen as these mutants do not exhibit the high rate of premature death observed in other SCN8A epilepsy mouse models." (PMID 38895634, 2024). "More than 200 mutations have been reported in SCN8A, where these mutations can manifest as both GOF and LOF, with the majority of epilepsy-linked variants being de novo GOF missense mutations." (PMID 39513870, 2024). "An example of the success of the application of these methods to registry data is the case of SCN8A-epilepsy and related disorders." (PMID 38466077, 2024). "Genetic variants of NaV1.1 (SCN1A), NaV1.2 (SCN2A), NaV1.3 (SCN3A), and NaV1.6 (SCN8A) sodium channels are involved in a broad spectrum of diseases, including several types of epilepsy." (PMID 37654020, 2024). "It has been shown that overexpression of Nav1.6 in the AIS results in an increase in spontaneous and repetitive firing, a possible rationale for why epilepsy-related mutations in SCN8A are mainly GOF with an effect on the action potential threshold." (PMID 39513870, 2024). "In one study, three patients with SCN8A-related epilepsy were suggested to take riluzole to treating seizures based on the hiPSC results." (PMID 39844857, 2024). "To further explore the clinical potential of these compounds, we tested their ability to increase resistance to induced seizures in CF1 mice and a mouse model of Scn8a-derived epilepsy." (PMID 38895634, 2024). "SCN8A (NaV1.6; OMIM 600702) is one of nine human genes encoding voltage-gated sodium channel α-subunits more recently implicated in epilepsy." (PMID 38233770, 2024). "Significantly, the Nav1.2/Nav1.6 channels are encoded by epilepsy-associated ion channel genes SCN2A and SCN8A." (PMID 38091244, 2024). "In fact, pathogenic variants of SCN1A/NaV1.1, SCN2A/NaV1.1, SCN3A/NaV1.1, SCN8A/NaV1.6, and SCN1B/β1, which are expressed in the central nervous system, are important causes of different types of epilepsies, including mild and severe forms." (PMID 37654020, 2024). "In summary, we evaluated the ability of four drugs to increase resistance to induced seizures in a mouse model of SCN8A epilepsy." (PMID 38895634, 2024). "Mutations in several NaV-α subunits were associated with epilepsy, including NaV1.1 (SCN1A), NaV1.2 (SCN2A), NaV1.3 (SCN3A), NaV1.6 (SCN8A), and NaV1.7 (SCN9A)." (PMID 39728106, 2024). "SCN1A, SCN2A, SCN3A, SCN8A, SCN9A, SCN11A, and SCN1B sodium channel gene mutations were intimately associated with epilepsy and displayed significant heterogeneity in pathogenesis and clinical symptoms." (PMID 38174099, 2023). "Nav channel mutations are related to epilepsy, including α subunits, such as Nav1.1 (SCN1A), Nav1.2 (SCN2A), Nav1.3 (SCN3A), Nav1.6 (SCN8A), and Nav1.7 (SCN9A), and the β subunit (SCN1B)." (PMID 38174099, 2023). "SVA-lncRNA AK057321 upregulates a wide variety of neurodevelopmental and neurological disease genes containing intronic SVAs beyond CDK5RAP2 including SCN8A, an epilepsy and intellectual disability sodium channel gene with a human-specific intronic SVA_D." (PMID 36997626, 2023). "For SCN2A and SCN8A, GOF is associated with an early-onset epilepsy phenotype including self-limited (familial) infantile epilepsy (SeLIE) or DEE." (PMID 36877742, 2023). "Human-specific SVAs in microcephaly CDK5RAP2 and epilepsy SCN8A gene introns repress their expression via transcription factor ZNF91 to delay neuronal maturation." (PMID 36997626, 2023).
epilepsy (continued). "A total of five cases of sudden unexpected death in epilepsy (SUDEP) occurred in patients with SCN1A, SCN2A, and SCN8A variants." (PMID 38174099, 2023). "Scn8a and Slc7a11 are the two most recently identified genes that can modify aspects of epilepsy in Kcna1 KO mice." (PMID 37240170, 2023). "Although epilepsy caused by the KCNQ2, KCNQ3, PRRT2, SCN2A and SCN8A gene are relatively benign, in our study, more than 18 genes caused epilepsy accompanied by the intellectual disability and more than 14 genes caused syndromes with epilepsy." (PMID 35571021, 2022). "VGSCs are known to play an important role in neuronal excitability and epilepsies; especially mutations in VGSC subunit genes such as SCN1A, SCN2A, SCN3A, and SCN8A have been found to cause human epilepsies." (PMID 35860491, 2022). "SCN8A has been reported to influence epilepsy at four months of early life and can affect the development." (PMID 35801810, 2022). "Voltage-gated sodium channels (VGSCs) play a critical role in generation of action potentials, SCN1A, SCN2A, SCN3A, SCN8A and SCN1B have been identified to be associated with a spectrum of epilepsy phenotypes and neurodevelopmental disorders." (PMID 36006933, 2022). "These cells share neuronal genes expressed in central excitatory neurons such as Kcna1, Kcnq2, Kcnq3, Scn1a, Scn8a, genes that are relevant to epilepsy." (PMID 36192157, 2022). "We found increased oligodendrogenesis and myelination specifically within the seizure network in two models of generalized epilepsy with absence seizures (Wag/Rij rats and Scn8a+/mut mice), evident only after epilepsy onset." (PMID 35501379, 2022). "Patients with SCN8A epilepsies are at an elevated risk of sudden unexpected death in epilepsy (SUDEP); SUDEP was reported in ~10% of patients with SCN8A‐related disorders in a recent systematic review of 56 studies (N = 235 patients)." (PMID 35802036, 2022). "Epilepsy caused by the KCNQ2, KCNQ3, PRRT2, SCN2A and SCN8A gene are relatively benign with mild symptoms and consequences." (PMID 35571021, 2022). "As to SCN8A-related epilepsy, a recent study showed that KD therapy was effective in 55.56% (5/9) of patients." (PMID 35160058, 2022). "Using multiple prediction algorithms, R639C was predicted to have possible pathogenic effects on Nav1.6 function and shared similar prediction scores to the recurrent SCN8A epilepsy mutation R850Q." (PMID 35805192, 2022). "SCN8A-DEE individuals are predisposed to early death, including sudden unexplained death in epilepsy (SUDEP)." (PMID 35234610, 2022). "This case demonstrates that epilepsy surgery reduced seizure burden in a patient with SCN8A-related epilepsy granting him short-term seizure freedom after resection, and then decreased seizure frequency after relapse compared to the preoperative baseline." (PMID 35492509, 2022). "NBI-921352 is currently being developed for both SCN8A-DEE epilepsy and adult focal-onset seizures by Neurocrine, 2019." (PMID 35234610, 2022). "The preliminary observations in this case series of patients with SCN8A‐epilepsy support further investigation into fenfluramine‐mediated improvement in non‐seizure comorbidities." (PMID 35802036, 2022). "SCN1A, SCN2A, SCN3A, and SCN8A genes which individually encode voltage-gated sodium channels, that is NaV1.1, NaV1.2, NaV1.3, and NaV1.6, are related to early onset epilepsies." (PMID 34276290, 2021). "Advanced search was done using the following keyword combinations: SCN1A mutations in epilepsy, SCN1B mutations in epilepsy, SCN2A mutations in epilepsy, SCN3A mutations in epilepsy, SCN8A mutations in epilepsy and functional studies of VGSCs in epilepsy." (PMID 33841294, 2021). "For genes associated with neonatal and infantile epilepsies, including KCNQ2, KCNT1, PRRT2, and SCN8A, we found that EMR usage was concentrated in the first year of life." (PMID 34031551, 2021).
epilepsy (continued). "Various clinical reports have shown that SCN8A-related epilepsy patients benefit from VGSC blockers, contrasting their inefficacy, or even detrimental effects in DS." (PMID 32134913, 2020). "NaV1.1 (SCN1A), NaV1.2 (SCN2A), NaV1.3 (SCN3A), NaV1.6 (SCN8A) and NaV1.7 (SCN9A) are genes whose mutations are related to epilepsy." (PMID 33013363, 2020). "One possible correlation of SUDEP with SCN8A-related epilepsy is the presence of NaV1.6 in heart muscles and tissues, being broadly expressed within ventricular myocytes." (PMID 33013363, 2020). "We did not identify pathogenic variants in the cardiac‐expressed SCN5A gene in our cohort or in the epilepsy‐associated genes SCN2A and SCN8A." (PMID 32449611, 2020). "Five different genes that encode alpha subunits of sodium ion channels have been reported to have mutations that lead to epilepsy; these include SCN1A, SCN2A, SCN3A, SCN8A, and SCN9A, and epilepsy-inducing mutations have also been reported in SCN1B." (PMID 33102526, 2020). "Phenytoin demonstrated effectiveness in decreasing seizure episodes in several patients with SCN8A-related epilepsies, however, side effects during prolonged use are very common." (PMID 33013363, 2020). "Therefore, to assess whether inhibition of Nav1.6 can be a novel treatment strategy for DS, also applicable for epilepsy caused by SCN8A gain-of function mutations and perhaps also epilepsy in general, we tested two compounds that selectively inhibit NaV1.6 channels." (PMID 32134913, 2020). "Resurgent currents are also enhanced by pro-excitatory disease mutations in other voltage-gated sodium channel isoforms which are associated with pain, myotonia congenital, long-QT syndrome, and SCN8A epilepsies." (PMID 31558572, 2019). "Such an approach already shows promise for personalizing therapies for epilepsy cases arising from gain-of-function mutations in ion-channel subunit genes (e.g., GRIN2A, GRIN2B, SCN8A)." (PMID 30089840, 2018). "In conclusion, we report three novel epilepsy diagnoses in SCN8A, all of which were located in an alternate copy of exon 5 (exon 5 A) and overlooked by clinical exome sequencing." (PMID 29121005, 2018). "Within the past year, de novo mutations of human SCN8A detected by exome sequencing have revealed a role for Nav1.6 in epilepsy and intellectual disability." (PMID 24194747, 2013). "In the same way, several DEEs caused by mutations in CDKL5, DNM1, KCNT1, SCN1A, SCN2A, SCN8A, and UBA5 genes, which present severe pharmaco-resistant epilepsy, are increasingly becoming targets for RNA molecules that aim to restore neuronal excitability and network function." (PMID 41244709, 2025). "Histological analysis showed that Scn8a knockdown in the hippocampus did not prevent neuronal loss associated with epilepsy, but reduced reactive gliosis." (PMID 39937026, 2025). "There is a need for increased research funding to understand SCN8A-RD and related epilepsies." (PMID 40830973, 2025). "While NaV1.6 was known to play a critical role in neuronal excitability since the mid-1990’s, it wasn’t until 2012 that the first pathogenic SCN8A variant was identified in a child with DEE and sudden unexpected death in epilepsy (SUDEP)." (PMID 40830973, 2025). "The results showed that ASO treatment could reduce Scn8a transcript abundance in a dose‐dependent trend, proving the potential for the treatment of SCN8A‐related epilepsy." (PMID 39526481, 2024). "Thus, further research will be required to better understand the therapeutic potential of modulating the noradrenergic system in SCN8A-derived epilepsy." (PMID 38895634, 2024). "Although sodium channel blockers may be beneficial in the treatment of epilepsy related to GOF variants in SCN2A and SCN8A, it is also known that sodium channel blockade may induce spasms or worsen them." (PMID 38540325, 2024).